EGFR (epidermal growth factor receptor)
Diseases named in the same sentence as EGFR in open-access papers (continued):
Sharing a sentence is not in itself a finding about the gene and the disease.
tumor (continued). "In combination with a specific EGFR inhibitor, all major tumor-associated phenotypes could be rescued." (PMID 34766923, 2021). "Elevated expression of PD-L1 on tumour cells is frequently secondary to induction by TILs, or driven by driver mutations, e.g., mutations in epidermal growth factor receptor (EGFR), via signalling through the PI3K-AKT-STAT3/mTOR pathway, hindering activation of TILs." (PMID 34968365, 2021). "Taken together, this study reveals that EGFR inhibitor history and tumor mutation load may influence the prognosis of patients even at the terminal disease stage." (PMID 33787673, 2021). "For the tumor samples with EGFR mutation, the ΔCT value could reflect the relative level of EGFR mutation in the tumor sample." (PMID 34692766, 2021). "Therefore, the pre-analytical steps for maximizing the tumor-derived nucleic acid concentration and ultra-sensitive analytical techniques were essentially required to achieve the optimal sensitivity of the EGFR mutation." (PMID 33435996, 2021). "Western blotting confirmed that DBZ reduced the levels of the active NOTCH1 (cleaved NOTCH1) and its target HES1 protein and that Erlotinib lowered the EGFR phosphorylation level in H3118 xenografts, suggesting that tumor suppression was caused by on-target effects of each drug." (PMID 33473104, 2021). "The study found that EGFR mutations were observed in 61.3% (57/93) of tumours." (PMID 34804960, 2021). "Interest in EGFR as a potential treatment target stemmed from observed high surface expression in more than 90% of studied ASCC patient biopsies with increased expression associated with tumor progression." (PMID 34062753, 2021). "Moreover, in patients with metastatic NSCLC, ctDNA has been approved as a non-invasive alternative to tumor biopsy samples to facilitate the detection of EGFR (epidermal growth factor receptor)-activating mutations." (PMID 33777757, 2021). "Interestingly, the identified kinases, such as MAPK1 and EGFR, were associated with tumor proliferation, invasion, apoptosis, and angiopoiesis." (PMID 34367282, 2021). "The EGFR target itself also has weak antigenicity, which limits its ability to cause a long-lasting and stable effect; this ability declines even further with tumor development." (PMID 34568049, 2021). "Furthermore, EGFR mutations are frequently lost or gained between the initial tumor and recurrence while molecular alterations, such as EGFR amplification, remain persistent unchanged." (PMID 34926242, 2021). "Tumours with the EGFRvIII mutation, similar to the common oncogenic EGFR missense mutations, show a constitutive PLCγ signalling but no MAP-kinase/ERK activation could be found at a high level of EGFRvIII expression." (PMID 35052732, 2021). "Through the review of the published studies, we discovered the role of ARID1A alterations or expression loss in the regulation of Bcl-2 expression and apoptosis of tumor cells which might participate into the resistance to EGFR-TKIs." (PMID 34715776, 2021). "Our analysis of the mechanisms of gene dysregulation indicated that EGFR expression is significantly associated with colon polyps (p = 0.028) and primary tumors p = 0.04029) but less associated with metastasis or recurrent tumor." (PMID 34512327, 2021). "In two patients, VAF of EGFR mutations in cfDNA was concordant with tumor volume changes." (PMID 34680416, 2021). "In vivo studies using mouse models showed that the absence of EGFR and its downstream signaling by genetically deleting the EGFR in tumour cells led to a significantly diminished infiltration of FoxP3 expressing Treg cells in EGFR deficient tumours in comparison to wt EGFR tumours." (PMID 35052732, 2021). "Therefore, tumor genotyping, including EGFR mutation testing, is a particularly important step in predicting sensitivity to targeted therapies in many patients diagnosed with NSCLC, especially in Asia." (PMID 34574036, 2021).
tumor (continued). "In some clinical settings in which tissue is limited and/or insufficient for molecular testing, physicians may use a plasma circulating tumor DNA assay to identify EGFR mutations." (PMID 34638411, 2021). "The subclonal presence of EGFR-TKI-resistance alterations raises the question of whether these mutations would be detected in a tumour biopsy." (PMID 33741979, 2021). "KRAS, BRAF, and PIK3CA mutations are highly concordant between primary tumors and distant metastatic CRC tumors, indicating that either type of tumor tissue could be useful as a source to detect KRAS mutations for the selection of anti-EGFR therapy." (PMID 33652647, 2021). "When a tumor progresses after EGFR targeted therapy, EGFR T790M mutation is found in 50% of cases." (PMID 34208111, 2021). "Epidermal growth factor receptor (EGFR) signaling and components of the fibrinolytic system, including urokinase-type plasminogen activator (uPA) and thrombomodulin (TM), have been implicated in tumor progression." (PMID 33886813, 2021). "However, post-TKI tumour biopsies have confirmed KRAS mutations in new osimertinib resistance in conjunction with new EGFR mutations, with resistance ameliorated via Ras-ERK inhibition in vitro." (PMID 34069119, 2021). "Notably, a significantly lower prevalence of actionable EGFR alterations was presented in patients with high-risk NMGs signature but accompanied with a more inflame immune tumor microenvironment." (PMID 34760888, 2021). "Moreover, EGFR expression was associated with poor prognostic parameters, such as higher tumor grade, higher mean Ki67 index, poor disease-free survival, and higher frequency of axillary metastasis." (PMID 34150374, 2021). "However, sputum has been considered to be unsuitable for EGFR mutation analysis because it contains many normal cells, such as bronchial epithelium and inflammatory cells, with tumor cells comprising < 1% of the total number of cells in sputum." (PMID 33757469, 2021). "After compiling ddPCR AF, NGS AF, and eLB current signal for EGFR mutations at each time point, we examined the correlations between ctDNA detection modalities for EGFR mutation detection and between each ctDNA detection modality and calculated tumor volume." (PMID 34283064, 2021). "Both the EGFR mutations were positive in the tumor of the tongue as the primary site." (PMID 33968826, 2021). "Further, high PD-L1 expression is not only found to accelerate skin carcinogenesis but also associated with tumor differentiation, vascular invasion, and resistance to epidermal growth factor receptor (EGFR) tyrosine kinase inhibitor treatment in non-small cell lung cancer (NSCLC)." (PMID 34631591, 2021). "Differences in tumor mutational profile, location, histology, and survival outcomes were compared in patients with EGFR- versus BRAF-mutated tumors, and microarray data from The Cancer Genome Atlas was used to assess differential gene expression between the groups." (PMID 34625582, 2021). "Relationship between the MF of TKI‐sensitizing EGFR mutation and tumor response to osimertinib." (PMID 33131198, 2021). "This review shows the potential utility of CTC parameters for obtaining information, such as protein expression and gene mutations (PD-L1 and EGFR, respectively), about primary tumours and metastases and the applicability of such information for the management and design of therapy." (PMID 34834295, 2021). "However, tumours overexpressing mutant forms of the EGFR have previously been associated with a “lymphocyte depletion” phenotype." (PMID 35052732, 2021).
tumor (continued). "We believe that in future research, the incorporation of noninvasive features such as pathological features and tumor marker features into the comprehensive prediction model may be more helpful for improving the predictive ability for EGFR mutation." (PMID 33314737, 2021). "Taken together, these findings indicate that interaction of IL-26 and EphA3 induces increased phosphorylation of AKT and JNK not only in murine TNBC but also in human TNBC, hence activating the EGFR-TKI-associated bypass pathway to result subsequently in tumor growth." (PMID 34021125, 2021). "Liu et al36 reported that EGFR mutation could be predicted by five radiological features that were divided into three groups: CT attenuation energy, tumor main direction, and texture defined by wavelets and laws (AUC 0.647)." (PMID 33314737, 2021). "We have developed a new approach to identify tumor lesions ≥ 3 mm in the pancreas by positron emission tomography (PET) with a new intraperitoneally administered 64Cu-labeled anti-epidermal growth factor receptor (EGFR) antibody (encoded as NCAB001), called 64Cu-NCAB001 ipPET." (PMID 35056963, 2021). "By relatively quantifying the EGFR mutations in tumor tissue according to ΔCT value, patients with a low ΔCT value of EGFR mutations could receive EGFR-TKI treatment because they would benefit the most." (PMID 34692766, 2021). "In Brazil, data from a retrospective cohort study from the year 2014 indicate that around 50% of patients with metastatic adenocarcinoma were referred for molecular testing, among whom, 24% had a tumour with positive EGFR activating mutation and 87% received an EGFR-tyrosine kinase inhibitor." (PMID 34567264, 2021). "Blakely CM et.al pointed out that tumor genomic complexity increased with the prolongation of EGFR-TKIs treatment, a change that, sometimes along with the co-mutation of other genes, can promote tumor development or limits EGFR inhibitor response." (PMID 34034713, 2021). "In addition, GC1118 is a novel, fully humanized anti-EGFR IgG1 antibody that displays inhibitory effects against patient-derived xenografts from CRC tumours with a KRAS mutation, especially in those with elevated expression of high-affinity ligands." (PMID 34663410, 2021). "Further studies exploring the impact of the primary tumor side on the prognostic outcomes of BRAF-mutated mCRC treated with anti-EGFR agents may be quite valuable." (PMID 34946284, 2021). "In addition to EGFR inhibitor history and tumor somatic mutation burden, we also found that tumor location within the lung and patient performance status score were associated with survival outcome." (PMID 33787673, 2021). "Suppression of this pathway by capmatinib may bypass the EGFR activating mutation and overcomes osimertinib resistance by targeting both tumor cells and CAFs." (PMID 33621951, 2021). "EGFR overexpression was found in 45–70% of TNBC patients and was associated with poor prognosis, so EGFR may be a potential tumor target for TNBC therapy." (PMID 34879870, 2021). "In addition, intra-tumor heterogeneity on CE CT images has also been reported to have the association with the EGFR mutations in NSCLC." (PMID 33428651, 2021). "The anticancer effects of AA on HCC were predicted to be associated with regulating tumor cell proliferation, apoptosis, angiogenesis, tumor invasion, and metastasis via various pathways such as the EGFR signaling pathway, ESR1 signaling pathway, and CCND1 signaling pathway." (PMID 33688369, 2021). "Genetic analysis of circulating tumor DNA in PE demonstrated an EGFR 19-del mutation." (PMID 33578601, 2021). "Based on the observed tumor cellularity, we would expect clonal EGFR mutations to present an allelic frequency of at least 0.31 on average (average cellularity divided by half), even in the absence of copy number gains, which are common in NSCLC and increase the observed allelic frequency." (PMID 33869038, 2021).
tumor (continued). "Strong EGFR expression is significantly associated with tumor growth and metastasis." (PMID 34560882, 2021). "Nevertheless, limited but remarkable studies have demonstrated that the detection of EGFR mutations in CTCs of NSCLC patients could mirror tumor heterogeneity and the emergence of clonal evolution under treatment selective pressure." (PMID 34073111, 2021). "However, data on the effect of anti-EGFR treatment in patients with CRC with a KRAS A146 tumor mutation are conflicting." (PMID 34820593, 2021). "One major advantage of a glucose-free, high protein nutritional intervention as a single therapeutic regimen in CRC patients may be the independence of tumor mutational profiles or EGFR cell surface expression levels." (PMID 34830971, 2021). "A more comprehensive understanding of these intricate pathways could thus enable targeted modulation of mutated EGFR tumours to enhance CD8 T-cell driven immunosurveillance and could improve responses to immunotherapies." (PMID 35052732, 2021). "Therefore, an ultrasensitive method for detecting tumor EGFR mutations in sputum sample is necessary." (PMID 33757469, 2021). "It is considered as an antagonist of EGFR and could cause an inhibition of tyrosine kinase-dependent tumor growth." (PMID 34439273, 2021). "Using machine learning to identify features that appeared in at least 10% of the iterations of the leave-one-out (LOO) loop, 5 semantic features (sex, tumor staging (N), histology, epidermal growth factor receptor (EGFR) mutation, and smoking attitude) and 6 radiomic image features were selected." (PMID 34912715, 2021). "EGFR expression is associated with tumor differentiation, apoptosis, metastasis, and angiogenesis." (PMID 34094906, 2021). "Interestingly, of the 1,308 cases with EGFR mutations found by NGS, 65.3% of the cases (854/1,308) also harbored non-EGFR mutations in 18 tumor-related genes." (PMID 34257561, 2021). "Studies have demonstrated that tumor TKI resistance is caused by the elimination of DMs containing EGFR VIII, which could reintegrate into the genome HSRs." (PMID 34568472, 2021). "SPP1 expression was higher in LUAD tumor tissues and in people with EGFR mutation." (PMID 34178613, 2021). "In combination with the specific EGFR inhibitor afatinib, all major tumor-associated phenotypes could be normalized." (PMID 34766923, 2021). "Exon-19 deletions (19del) and L858R substitution in exon-21 are the 2 classical EGFR mutations which could predict tumor responses to EGFR tyrosine kinase inhibitors (EGFR-TKIs) in NSCLC patients." (PMID 34257561, 2021). "In conclusion, the understating of the molecular basis of tumor heterogeneity in EGFR mutated NSCLC patients is crucial for designing combinatorial approaches targeting the bypass signaling pathways, preventing the onset of resistance mechanisms, and prolonging patient survival." (PMID 33922215, 2021). "This suggested that EGFR on-target resistance mutations might arise from the same primary tumor clones." (PMID 34385540, 2021). "The expression of miR-320d was significantly associated with distant metastasis, tumor size, and EGFR status, which means miR-320d might function as a tumor suppressor in EGFR-positive CRC." (PMID 34733314, 2021). "Unfortunately, our findings indicated that EGFR mutation has a little impact on tumor progression." (PMID 34589430, 2021). "EGFR mutation testing was performed on formalin-fixed paraffin-embedded (FFPE) specimens from primary tumor obtained from bronchoscopic biopsy or CT-guided core biopsy before any tumor-related treatment." (PMID 34692766, 2021). "While for oncogenes, the GB02 tumor has (nine/nine) EGFR mutations in all its portions." (PMID 33922652, 2021).
tumor (continued). "For example, one patient had a PTPN11 mutation thought to drive EGFR addiction and, hence, response to afatinib, and another patient had a tumor that was EGFR amplified and carried an additional allele on the amplicon, potentially underlying the sustained response observed." (PMID 34787778, 2021). "In this way, the ‘cold’ tumor microenvironment (typically seen in EGFR-mutated tumors) may be turned into an environment enriched with tumor-infiltrating lymphocytes." (PMID 34634633, 2021). "EAI045 could highly and selectively inhibit the proliferation of tumor cells with wild-type EGFR and the L858R/T790M mutation, and tumor volumes were significantly reduced after treatment." (PMID 34575576, 2021). "We expected that emetine may reduce the tumor growth of PC9-ErlR cells because these cells acquired erlotinib resistance through the EGFR (T790M) mutation." (PMID 34203709, 2021). "Our chimeric antigen receptor (CAR) T cell (2173 CAR T cells) clinical trial (NCT02209376) against epidermal growth factor receptor (EGFR) variant III (EGFRvIII) demonstrated successful trafficking of T cells across the blood–brain barrier into GBM active tumor sites." (PMID 34568006, 2021). "Patients whose tumours harbour EGFR mutations may be sensitive to EGFR tyrosine kinase inhibitors (TKIs), which are recommended treatment options in this setting." (PMID 33648453, 2021). "Promisingly, the measurement of exoNA may expand the utility of exosomes as potential diagnostic and prognostic tools in EGFR-mutated cancers as they could provide a more complete assessment of the evolving tumor and response to targeted therapies." (PMID 33855679, 2021). "The EGFR mutation correlated significantly with the ISP tumor histotype (p < 0.001)." (PMID 34885191, 2021). "EGFR mutated lung tumors expressed SALL4 to a significantly higher degree than non-tumor tissue." (PMID 34573282, 2021). "Given the complex and intricate nature of the TME, we hypothesize that the mutated EGFR signalling could be driving tumour cell-autonomous immunosuppression by more than one mechanism." (PMID 35052732, 2021). "Exosomes may be also useful in identifying tumor somatic mutations, such as EGFR activating mutations." (PMID 33937034, 2021). "Then, in mouse xenograft models, oral administration of SH-1028 at a daily dose of 5 mg/kg significantly inhibited proliferation of tumor cells with EGFR sensitive mutation (exon 19 del) and resistant mutation (T790 M) for consecutive 14 days, with no TKI-induced weight loss." (PMID 33986687, 2021). "Patients who discontinue EGFR inhibitor treatment have a higher risk of symptomatic progression and increase in tumor size, which may lead to a much more rapid progression of the cancer." (PMID 33787673, 2021). "The tumor volume in PC-9 (Del 19, EGFR sensitive mutation) or NCI-H1975 (L858R/T790M resistance mutation) xenograft model showed a significant reduction, indicating that SH-1028 could inhibit tumor growth in a dose-dependent manner." (PMID 33986687, 2021). "Therefore, we restricted our analysis on CD8B gene expression as a specific marker for CD8 T-cells and quantified the relative abundance of CD8 T-cells in LUAD tumours with EGFR oncogenic mutations compared to EGFR wild-type (Wt) LUADs." (PMID 35052732, 2021). "Similarly, clinical trial NCT01734915 (Detecting EGFR T790M Mutations from Circulating Tumor Cells) was initiated in 2012 and intended to assess EGFR mutations in CTCs isolated using the microfluidic CTC-chip." (PMID 33925308, 2021). "Some studies suggested EGFR gene mutation was associated with tumor differentiation." (PMID 35049681, 2021). "We speculate that genetic alterations, such as activating EGFR mutations, that are fundamental to and characteristic of tumorigenesis are widely present in tumor tissues and may also be detected in cfDNA." (PMID 33863951, 2021).